USP49 (ubiquitin specific peptidase 49)
Diseases named in the same sentence as USP49 in open-access papers:
USP49 is named in the same sentence as 27 diseases in open-access papers, as found by Europe PMC text mining. Sharing a sentence is not in itself a finding about the gene and the disease. The quoted sentences say what the papers report.
pancreatic cancer (8 papers, 2019 to 2025). "Clinically, decreased USP49 expression in patients with pancreatic cancer is associated with decreased FKBP51 expression and increased phosphorylation of AKT." (PMID 35884607, 2022). "Notably, Fbxo45 expression was negatively associated with USP49 expression in pancreatic cancer tissues." (PMID 35279684, 2022). "Interestingly, an SNP of a large linkage disequilibrium block containing USP49 gene is associated with breast cancer survival and USP49 functions as a tumor suppressor in pancreatic cancer." (PMID 30943264, 2019). "Functionally, Fbxo45 increases cell viability and motility capacity by targeting USP49 in pancreatic cancer cells." (PMID 35279684, 2022). "Fbxo45 serves as an oncoprotein to facilitate pancreatic oncogenesis by regulating the stability of the tumor suppressor USP49 in pancreatic cancer." (PMID 35279684, 2022). "Recently, a conserved F-box protein, Fbxo45, was shown to interact with USP49 in pancreatic cancer cells, resulting in increased cell viability and motility capacity." (PMID 35884607, 2022). "We observed the basal expression levels of Fbxo45 and USP49 in several pancreatic cancer cell lines." (PMID 35279684, 2022). "Similarly, FBXO45 facilitates pancreatic cancer progression by regulating the stability of the tumor suppressor USP49." (PMID 40021626, 2025). "Furthermore, we used bioinformatics to analyze the expression of Fbxo45 and USP49 in human pancreatic tumor samples." (PMID 35279684, 2022). "In contrast, USP49 was discovered as a deubiquitinase of FKBP51, which is a tumor‐suppressing protein in pancreatic cancer." (PMID 39497328, 2024). "USP49 has been identified as a novel modulator of the AKT pathway, which plays a key role in tumorigenesis and chemotherapy response in pancreatic cancer." (PMID 35884607, 2022).
colon cancer (6 papers, 2018 to 2025). "Whether and how the USP49-MITA axis regulates inflammatory diseases such as colitis and tumorigenesis such as colon cancer is of great interest and requires future investigations." (PMID 30943264, 2019).
colorectal cancer (5 papers, 2018 to 2024). A primary or metastatic malignant neoplasm that affects the colon or rectum. "Finally, we found that USP49 can increase cell sensitivity to etoposide (Eto)-induced DNA damage and that USP49-knockout mice are more susceptible to colorectal cancer induced by azoxymethane/dextran sulfate sodium (AOM/DSS)." (PMID 29748582, 2018). "We demonstrated a novel chemoresistance mechanism in colorectal cancer by performing in vitro and in vivo experiments that regulated the expression of USP49, which was found to be a transcription factor of miR-5000-3p." (PMID 34075026, 2021). "For instance, USP49 deubiquitinates and stabilizes Bcl‐2‐Associated Athanogene 2 (BAG2) which is a well‐known oncogenic protein that antagonizes apoptosis and enables adaptive response in colorectal cancer." (PMID 39497328, 2024).
esophagogastric junction adenocarcinoma (4 papers, 2024 to 2025). "USP49 drives malignant progression of esophagogastric junction adenocarcinoma by activating the SHC binding and spindle associated 1 (SHCBP1)/β-catenin/glutathione peroxidase 4 (GPX4) signaling pathway." (PMID 41035649, 2025). "Furthermore, USP49 is upregulated in adenocarcinoma of the esophagogastric junction and promotes cancer cell proliferation." (PMID 39497328, 2024). "In esophagogastric junction adenocarcinoma, however, SHCBP1 stability increases through deubiquitination via ubiquitin-specific peptidase 49 (USP49)." (PMID 41009347, 2025).
hepatocellular carcinoma (3 papers, 2020 to 2025). A malignant tumor that arises from hepatocytes. "Additionally, it has been revealed that lncRNA hepatocellular carcinoma-associated long non-coding RNA 1 (HLNC1) binds to USP49 and destabilizes it to promote the advancement of HCC." (PMID 41035649, 2025). "Furthermore, lncRNA HLNC1 was reported to bind to and destabilize USP49 to enhance hepatocellular carcinoma progression." (PMID 35279684, 2022).
gastric cancer (2 papers, 2024 to 2025). A primary or metastatic malignant neoplasm involving the stomach. "For instance, USP49 promotes the proliferation, metastasis, chemoresistance, and peritoneal metastasis in gastric cancer cells." (PMID 39497328, 2024). "However, in gastric cancer, USP49 stabilizes YAP1 through deubiquitination, and YAP1 in turn promotes the transcription of USP49, forming a positive feedback loop that drives the malignant progression of gastric cancer." (PMID 40607251, 2025).
glioma (2 papers, 2022 to 2023). A benign or malignant brain and spinal cord tumor that arises from glial cells (astrocytes, oligodendrocytes, ependymal cells). "Our study suggests that TRIM24, IDH1, LBR, HMG20B, USP49 and RCC1 were all highly expressed in glioma tissues and gliomar cell lines both at the mRNA and protein level." (PMID 36246611, 2022). "The RT-qPCR assay showed that the six signature genes (TRIM24, IDH1, LBR, HMG20B, USP49, and RCC1) were up-regulated in glioma cell lines in mRNA expression level." (PMID 36246611, 2022).
carcinoma in situ (1 paper, 2018). "Moreover, compared to the USP49-wild-type mice, the USP49-knockout mice displayed a notable increase in the number of macroscopically visible tumors as well as larger and more advanced tumors and an increased incidence of high-grade intraepithelial neoplasia and carcinoma in situ." (PMID 29748582, 2018).
endometrial cancer (1 paper, 2025). Primary or metastatic malignant neoplasm involving the endometrium (mucous membrane that lines the endometrial cavity).
esophageal squamous cell carcinoma (1 paper, 2025). Esophageal squamous cell carcinoma (ESCC) is a type of esophageal carcinoma (EC) that can affect any part of the esophagus, but is usually located in the upper or middle third. "USP49 promotes radioresistance in esophageal squamous cell carcinoma by stabilizing replication protein A 70 (RPA70) via homologous recombination repair." (PMID 41035649, 2025).
HIV-1 infection (1 paper, 2019). The type species of lentivirus and the etiologic agent of acquired immunodeficiency syndrome (AIDS). "Further, we aimed to elucidate the association between USP49 and A3G in the presence of Vif, which could occur during natural HIV-1 infection." (PMID 31397674, 2019). "When we transfected Vif and A3G at a ratio 1:1, the overexpression USP49 was found to inhibit HIV-1 infection and the inhibitory effect occurred in a dose-dependent manner." (PMID 31397674, 2019). "To determine the relevance of A3G regulation by USP49 in vivo, we performed intracellular staining to detect A3G protein levels in primary CD4+ T cells that were isolated from newly-diagnosed individuals with HIV-1 infections (n = 21)." (PMID 31397674, 2019).
lung carcinoma (1 paper, 2026). "Bioinformatics analysis demonstrates that these DUBs except USP47 are upregulated and overall survival analysis indicates that lower expression of these DUBs, except USP37 and USP49, is correlated with improved overall survival in lung cancer patients." (PMID 41399373, 2026). "Following the observation of altered expression levels of USP35, USP36, USP37, USP47, USP49, and OTUD6B in response to cisplatin treatment in lung cancer cells, both at the mRNA and protein levels, we sought to explore their significance in lung cancer." (PMID 41399373, 2026). "Multiplex RT-PCR showed distinct mRNA expression profiles of several DUB genes, including USP35, USP36, USP37, USP47, USP49, and OTUD6B in A549 lung cancer cells following exposure to cisplatin." (PMID 41399373, 2026). "Substantiating these findings, western blotting analysis confirmed the protein expression levels of USP35, USP36, USP37, USP47, USP49, and OTUD6B in cisplatin-treated lung cancer cells, mirroring the mRNA trends observed in non-treated counterparts except for OTUD6B." (PMID 41399373, 2026).
non-small cell lung carcinoma (1 paper, 2021). A group of at least three distinct histological types of lung cancer, including non-small cell squamous cell carcinoma, adenocarcinoma, and large cell carcinoma. "USP49 was also reported to inhibit non-small cell lung cancer cell growth by suppressing PI3K/AKT signaling." (PMID 34075026, 2021).
Obesity (1 paper, 2019). Accumulation of substantial excess body fat. "A recent study on exome sequencing indicates that USP49 is one of the frequently mutated genes associated with obesity which is recognized as a chronic inflammatory disease related to cardiovascular and respiratory diseases, type II diabetes, and cancers." (PMID 30943264, 2019).
osteoarthritis (1 paper, 2023). A noninflammatory degenerative joint disease occurring chiefly in older persons, characterized by degeneration of the articular cartilage, hypertrophy of bone at the margins and changes in the synovial membrane. "In osteoarthritis patients, the expression of USP49 was lower compared with normal healthy persons." (PMID 37359559, 2023).
virus infection (1 paper, 2019). "To investigate the function of USP49 in host defense against virus infection in vivo, we monitored survival of Usp49+/+ and Usp49-/- mice after intravenous (i.v.)injection of HSV-1." (PMID 30943264, 2019).
cancer (13 papers, 2018 to 2026). A tumor composed of atypical neoplastic, often pleomorphic cells that invade other tissues. "As a member of the deubiquitinase family, USP49 modulates protein stability and cellular signaling pathways by reversing ubiquitination, thereby regulating various cellular processes implicated in cancer progression." (PMID 39497328, 2024). "We show that loss of USP49 in different cancer cell lines impairs proliferation and increases aneuploidy." (PMID 36702832, 2023). "Collectively, these findings demonstrate that USP49 regulates Bax primarily through K29/K33/K63-linked ubiquitination and transcriptional upregulation, highlighting its role as a stress-responsive modulator of apoptosis and a potential therapeutic target in cancer." (PMID 42123680, 2026). "Numerous investigations have demonstrated that USP49 functions as a tumor suppressor in a variety of cancer types." (PMID 41035649, 2025). "Ubiquitin‐specific peptidase 49 (USP49) has emerged as a crucial player in human cancers, exerting multifaceted roles in tumorigenesis." (PMID 39497328, 2024). "Future research should focus on developing inhibitors that selectively target USP49 in cancer cells." (PMID 39497328, 2024). "As a deubiquitination enzyme, USP49 also plays an essential role in cancer development and chemoresistance by regulating the protein stability of oncogenes or tumor suppressors." (PMID 39497328, 2024). "Specifically, we show that the depletion of USP49 in different cancer cell lines impairs proliferation." (PMID 36702832, 2023). "The bioinformatics results also showed higher expression of Fbxo45 and lower expression of USP49 in cancer tissues than in normal tissues." (PMID 35279684, 2022). "A number of these studies have already been discovered in the literature, that USP49 was downregulated in several cancer as a tumor suppressor." (PMID 34075026, 2021). "Molecular mechanism assays revealed that USP49 binds to the miR-5000-3p promoter to increase the expression of miR-5000-3p, resulting in cancer cells sensitized to OXA." (PMID 34075026, 2021). "Notably, USP49 has garnered attention for its involvement in chemoresistance, wherein abnormal expression or dysregulated activity of USP49 contributes to the resistance of multiple cancer types to chemotherapeutic agents." (PMID 41035649, 2025). "Notably, USP49 has garnered attention for its involvement in chemoresistance, wherein aberrant expression or activity of USP49 confers resistance to diverse chemotherapeutic agents in different cancer types." (PMID 39497328, 2024). "USP49 has been reported as an oncogene in several cancer types." (PMID 39497328, 2024). "Given the promoting role of USP49 in resistance to platinum‐based chemotherapeutic drugs in human cancers, USP49 may also participate in RB progression or CBP resistance in RB." (PMID 39497328, 2024). "Several studies have revealed that USP49 acts as a tumor suppressor in multiple types of cancers." (PMID 35279684, 2022). "The upregulation of HLNC1 in HCC through HSF1 may partially enhance cancer progression via decreasing the level of USP49 mRNA and USP49 proteins were consistently downregulated." (PMID 32691951, 2020). "In addition, overexpression of USP49 sensitized cancer cells to chemotherapy." (PMID 34075026, 2021). "Our findings suggest that USP49 may be a potential target for cancer therapy." (PMID 29748582, 2018). "USP35, USP36, USP37, USP47, USP49, and OTUD6B play crucial roles in cancer progression and chemoresistance across various cancers, including NSCLC." (PMID 41399373, 2026). "At present, the research on USP49 is limited and its function in malignant tumors is not completely clear." (PMID 36061144, 2022).
tumor (12 papers, 2008 to 2026). "USP49 controls a number of cellular processes linked to tumor development by reversing ubiquitination, thereby modifying protein stability and cellular communication pathways." (PMID 41035649, 2025). "Moreover, we found that a low level of USP49 was dramatically associated with tumor grade (p = 0.0371)." (PMID 35279684, 2022). "It was shown that USP49 silencing significantly attenuated xenograft tumor growth and impaired resistance to CBP." (PMID 39497328, 2024). "USP49 showed a lower level in tumor tissues than in tumor-adjacent normal tissues, which was consistent with the bioinformatic results." (PMID 35279684, 2022). "Xenograft mouse experiments demonstrated that ectopic expression of Fbxo45 enhanced tumor growth in mice and that USP49 overexpression inhibited tumor growth in vivo." (PMID 35279684, 2022). "Among 60 cases with high expression of Fbxo45 in tumor tissues, 53 cases showed low USP49 expression (p = 0.0320)." (PMID 35279684, 2022). "USP49 was belonging to CRC-associated gene and found that can increase cell sensitivity to etoposide (Eto)-induced DNA damage and was suggested as a tumor suppressor during the development of CRC11,12." (PMID 34075026, 2021). "In line with this, we reveal a mechanism by which USP49 being regulated by miR-5000-3p, is related to chemoresistance and promotes tumor progression via the PI3K/AKT pathway in CRC." (PMID 34075026, 2021). "Notably, these inhibitory effects were reversed upon USP49 silencing, indicating that USP49 mediates the tumor-suppressive effects of FBXO2 depletion." (PMID 41035649, 2025). "Notably, overexpression of USP49 in Panc-1 cells dramatically inhibited tumor growth in mice, displaying a reduction in the weights and volumes of tumor mass." (PMID 35279684, 2022). "Importantly, USP49 partly rescued the Fbxo45-mediated promotion of cell growth and migration and invasion in PC cells, indicating that Fbxo45 performs its tumor promoter function via degradation of USP49 in PC cells." (PMID 35279684, 2022). "Another, according to the Context++ score percentile (score > 70) in the TargetScanHuman, we selected the tumor suppressor USP49 with high Context++ score for the subsequent analysis when compared with IL17RD (score = 58), FOSB (score = 88) and SHROOM4 (score = 21)." (PMID 34075026, 2021). "Furthermore, USP49 can also improve chemoresistance and inhibit tumor progression by mediating FKBP51‐AKT signaling." (PMID 32691951, 2020). "As a result, maintaining the level of USP49 plays a critical role in tumor suppression." (PMID 32691951, 2020). "The tumor incidence in USP49-knockout mice was >90%, but it was <50% in USP49-wild-type mice." (PMID 29748582, 2018). "Therefore, USP49 promotes RB tumor growth and CBP resistance in vivo." (PMID 39497328, 2024). "Moreover, USP49 knockdown also suppressed tumor and CBP resistance in vivo." (PMID 39497328, 2024). "However, the role of miR-5000-3p in tumor resistance of CRC has not been reported, and how USP49 expression present in CRC is unclear." (PMID 34075026, 2021).
USP49 also shares sentences with these, for which no sentence is quoted: breast carcinoma (2 papers); infection (2); mesothelioma (2); breast tumours (1); colitis (1); intraepithelial neoplasia (1); respiratory diseases (1); retinoblastoma (1); type II diabetes (1).